MSLN (mesothelin)
Diseases named in the same sentence as MSLN in open-access papers (continued):
Sharing a sentence is not in itself a finding about the gene and the disease.
endometriosis (2 papers, 2019 to 2024). The growth of functional endometrial tissue in anatomic sites outside the uterine body. "Sanjie Zhentong capsules demonstrate efficacy in regulating sex hormones, reducing serum FOLR1 and MSLN expression, alleviating pain, shrinking adnexal masses, decreasing uterine size, and improving uterine artery blood flow in endometriosis patients." (PMID 39465861, 2024). "Examining the impact of Sanjie Zhentong capsules on hormone levels and serum expression of folate receptor 1 (FOLR1) and Mesothelin (MSLN) in endometriosis patients." (PMID 39465861, 2024). "In summary, the analgesic capsules can regulate sex hormones in patients with endometriosis, reduce the levels of serum FOLR1 and MSLN, alleviate pain, decrease the size of nodules, improve uterine size, and enhance blood flow in the uterine arteries." (PMID 39465861, 2024). "Comparative analyses encompassed uterine artery hemodynamic parameters, ultrasound (B-mode) findings, Visual Analog Scale scores, traditional Chinese medicine symptom scores, Endometriosis Health Profile-30 scores, and serum levels of FOLR1, MSLN, and sex hormones before and after treatment." (PMID 39465861, 2024).
epithelial ovarian tumors (2 papers, 2006 to 2024). "Both MUC16 and mesothelin (MSLN) are highly expressed in epithelial ovarian tumors, and both soluble and cell surface-associated forms of native MUC16 interact with MSLN." (PMID 38758220, 2024). "MUC16 was co-expressed and interacted with mesothelin proteins in both ovarian epithelial tumors and pancreatic ductal carcinoma, and the combination of the two promoted cancer metastasis and invasion." (PMID 38758220, 2024). "In conclusion, we have provided new data on the interaction between two glycoproteins, mesothelin and MUC16, whose expression is highly upregulated by epithelial ovarian tumors." (PMID 17067392, 2006).
glaucoma (2 papers, 2021 to 2022). Increased pressure in the eyeball due to obstruction of the outflow of aqueous humor. "Except for MSLN, the proteins encoded by these genes have not been reported to be associated with glaucoma." (PMID 34440692, 2021). "The finding of MSLN in the tear might be stressed, however, if one considers the increased level of extracellular matrix compounds as a pattern for CRVO and glaucoma; the presence of MSLN seems reasonable due to its importance in cell adhesion as well as PPR4 and ACTB." (PMID 36498980, 2022).
Hypertension (2 papers, 2014 to 2021). The presence of chronic increased pressure in the systemic arterial system. "Mesothelin was additionally affected by bronchitis, elevated C-reactive protein and current hypertension." (PMID 34768395, 2021). "This is in contrast to our study where lower concentrations of mesothelin were observed in patients with hypertension." (PMID 25469901, 2014).
large cell carcinoma (2 papers, 2017 to 2022). A malignant epithelial neoplasm composed of large, atypical cells. "An analysis of lung tumors showed that MSLN was also overexpressed in half of ADCs, in large cell carcinomas, and in SCC, but was absent in SCLC43." (PMID 35197508, 2022).
large cell lung cancer (2 papers, 2011 to 2023). "NCI-H460 (large cell lung cancer), A549, NCI-H322 and NCI-H522 (adenocarcinomas) are NSCLC cell lines that express variable levels of mesothelin." (PMID 36911670, 2023).
lung fibrosis (2 papers, 2022 to 2024). "Nevertheless, recent evidence highlights the role of mesothelin (MSLN which binds cancer antigen CA-125 also known as MUC16) in pulmonary fibrosis, suggesting that MSLN is involved in cell adhesion." (PMID 39361584, 2024).
mucinous adenocarcinoma (2 papers, 2022 to 2024). An invasive adenocarcinoma composed of malignant glandular cells which contain intracytoplasmic mucin. "Significant results (P< 0.05) included associations with WNT11 and FBXL16 and body mass index (BMI), MSLN and mucinous adenocarcinoma, and SLC38A11 and metastasis." (PMID 38680862, 2024).
osteosarcoma (2 papers, 2023 to 2025). A usually aggressive malignant bone-forming mesenchymal neoplasm, predominantly affecting adolescents and young adults. "Most gene targets commonly investigated in ACT of other solid tumors except osteosarcoma, such as CEACAM1, PSCA, MSLN, IL13RA2, and GPC3, showed low or nonspecific expression in osteosarcoma compared with adjacent normal tissues." (PMID 37457661, 2023).
pericarditis (2 papers, 2023 to 2024). An inflammatory process affecting the pericardium. "While pericarditis and other serosal membrane toxicities are theoretical on-target off-tumor toxicities of mesothelin-targeted therapeutics like LMB-100, these were the first two occurrences of pericarditis in pancreatobiliary cancer patients receiving LMB-100." (PMID 38706610, 2024). "Pericarditis with the combination was not reproducible in a transgenic murine model containing human MSLN." (PMID 38706610, 2024).
peritoneal cancer (2 papers, 2020 to 2024). A peritoneum cancer that is located in the inside of the abdomen. "The cell surface glycoprotein Mesothelin is overexpressed in ovarian, fallopian tube, endometrial, cervical and primary peritoneal cancer and, therefore, might become a particular interesting tumor target in gynecologic oncology." (PMID 32815024, 2020).
pneumonitis (2 papers, 2024). An inflammatory process affecting the lung parenchyma. "Therefore, future studies of anti‐mesothelin CAR T cells should carefully select patients with underlying lung disease and initiate mitigation strategies including early use of steroids to treat pneumonitis." (PMID 39548594, 2024).
viral infection (2 papers, 2018 to 2021). "While tumor associated antigens, such as mesothelin, often do not induce a robust immune response, evidence suggests it is possible to generate an anti-tumor response by presenting the tumor antigen in an immunogenic context, such as by expressing the protein in a viral infection." (PMID 29474384, 2018).
adenoid cystic carcinoma (1 paper, 2018). A malignant tumor arising from the epithelial cells. "The mucoepidermoid carcinoma, the adenoid cystic carcinoma, the non-specific adenocarcinoma and some of the salivary duct carcinoma samples included more MSLN positive cells in the cancer tissues." (PMID 30558663, 2018).
adenoma (1 paper, 2015). A neoplasm arising from the epithelium. "The majority of the adenoma cells that expressed mesothelin exhibited slight diffuse cytoplasmic staining." (PMID 25789005, 2015). "Conversely, mesothelin expression was detected in adenoma and carcinoma cells." (PMID 25789005, 2015).
Allergy (1 paper, 2023). An allergy is an immune response or reaction to substances that are usually not harmful. "The levels of FS (Follistatin), Erb-B2 receptor tyrosine kinase 2 (ERBB2), TGFR2 (transforming growth factor beta receptor 2), MSLN (mesothelin) and TM (thrombomodulin) were influenced by Benzodiazepines and PRS27 (serine protease 27) by allergy drugs." (PMID 37667404, 2023).
Anxiety (1 paper, 2016). Intense feelings of nervousness, tension, or panic often arise in response to interpersonal stresses. "In models with correction for comorbid anxiety, all other markers remained significant (P<0.05) with the exception of MSLN and ANG2 in the atypical versus control comparison (P<0.10)." (PMID 27404283, 2016).
apocrine gland adenocarcinoma (1 paper, 2024). "Low mesothelin expression was found in a few epithelial tumors, including the apocrine gland adenocarcinoma of the anal sac and mammary gland tumors, whereas none of the mesenchymal tumors expressed substantial mesothelin levels." (PMID 39315086, 2024).
autoimmune disease (1 paper, 2018). A disorder resulting from loss of function or tissue destruction of an organ or multiple organs, arising from humoral or cellular immune responses of the individual to their own tissue constituents. "This suggests that no significant anti-mesothelin autoimmune disease was induced in the mice." (PMID 29474384, 2018).
biphasic mesothelioma (1 paper, 2023). "The one patient with biphasic mesothelioma who had a high H‐score also had increased survival, but more cases are required to determine whether MSLN expression also has prognostic relevance to non‐epithelioid subtypes." (PMID 37040900, 2023).
Cachexia (1 paper, 2022). Severe weight loss, wasting of muscle, loss of appetite, and general debility related to a chronic disease. "Moreover, cluster 10, annotated as mesothelium originated progenitor cells with specific expression of ITLN1 and MSLN, was almost exclusively found in VAT in non-cachexia patients." (PMID 36376273, 2022).
colorectal tumour (1 paper, 2024). "Previous studies have demonstrated the ability of anti‐mesothelin adoptive cell therapies using CAR T43, 44, 45, 46 and CAR NK cells, to specifically target and kill MSLN‐positive gastric and colorectal tumour cells." (PMID 39548594, 2024).
cyst (1 paper, 2024). A sac-like closed membranous structure that may be empty or contain fluid or amorphous material. "The characteristic microscopic appearance of a single layer of cuboidal mesothelial cells lining the cyst wall, along with positive staining for specific mesothelial markers such as calretinin, WT-1, mesothelin, and HBME, aids in the diagnosis of pelvic mesothelial cysts." (PMID 39759741, 2024).
delirium (1 paper, 2026). A disorder characterized by confusion; inattentiveness; disorientation; illusions; hallucinations; agitation; and in some instances autonomic nervous system overactivity. "Other notable proteins robustly associated with delirium in our proteomic analysis are BCAN, SELENOP, AREG and MSLN." (PMID 41286463, 2026). "Overall, 14 out of the 19 stability-selected proteins still had a significant effect on incident delirium in the training set; however, only the AREG and MSLN proteins were consistently selected in the dementia-free subcohort (selection frequency >0.5)." (PMID 41286463, 2026).
ductal carcinoma (1 paper, 2014). "ERC/mesothelin is frequently expressed in ductal carcinoma, but not in normal pancreas." (PMID 25347530, 2014).
esophageal squamous cell carcinoma (1 paper, 2015). Esophageal squamous cell carcinoma (ESCC) is a type of esophageal carcinoma (EC) that can affect any part of the esophagus, but is usually located in the upper or middle third. "In contrast, for esophageal squamous-cell carcinomas only a MSLN amplification rate of 3% (N = 109) was observed." (PMID 26172299, 2015).
influenza (1 paper, 2020). An acute viral infection of the respiratory tract, occurring in isolated cases, in epidemics, or in pandemics; it is caused by serologically different strains of viruses (influenzaviruses) designated A, B, and C, has a 3-day incubation period, and usually lasts for 3 to 10 days. "Mesothelin, another Mucin-16 binding partner, potentially home MBCs to lungs, consistent with reports of influenza-specific lung-resident MBCs in the mouse." (PMID 33116135, 2020).
intraductal papillary mucinous neoplasms (1 paper, 2022). "However, it is not clear at which moment of cancer development the MSLN expression begins: while the pancreatic intraepithelial neoplasia does not show MSLN expression, MSLN is observed in the intraductal papillary mucinous neoplasms, with a higher frequency in the invasive lesions." (PMID 36009489, 2022).
invasive carcinoma (1 paper, 2015). A carcinoma that is not confined to the epithelium, and has spread to the surrounding stroma. "Among the 37 cases of IPMN, mesothelin expression was observed in 46.2% (12 out of 26) of the samples from L-H grade dysplasia and 81.8% (nine out of 11) of the samples from invasive carcinomas." (PMID 25789005, 2015). "Luminal membrane mesothelin expression was observed in 15.4% (four out of 26) of the L-H grade dysplasia samples and 54.5% (six out of 11) of the invasive carcinoma samples." (PMID 25789005, 2015). "Among the 37 IPMNs, mesothelin expression was observed in 21 samples (56.8%), including 46.2% (12 out of 26) of the L-H dysplasia and 81.8% (9 out of 11) of the invasive carcinoma samples (P=0.071)." (PMID 25789005, 2015). "Cytoplasmic mesothelin expression was observed in 38.5% (10 out of 26) of the L-H grade dysplasias and 63.6% (seven out of 11) of the invasive carcinomas." (PMID 25789005, 2015).
leukopenia (1 paper, 2018). "Unlike chemotherapies, leukopenia is not one of the side effects of anti-mesothelin immunotoxins." (PMID 30441807, 2018).
lobular carcinoma (1 paper, 2014). "MSLN was positive in 13 out of 76 IDC-NOS and one mixed ductal and lobular carcinoma." (PMID 25506917, 2014).
malignant glioma (1 paper, 2017). A grade III or grade IV glioma arising from the central nervous system. "Here, we report the immunological significance of mesothelin in human malignant glioma." (PMID 29113296, 2017). "However, no formal link between mesothelin and primary malignant gliomas in humans has been establishedat this point." (PMID 29113296, 2017).
malignant peritoneal mesothelioma (1 paper, 2025). An aggressive malignant mesothelioma that arises from the peritoneum. "Ongoing trials, such as NCT03608618 and NCT04660929, are evaluating CAR-Ms that target mesothelin and HER2, respectively, in patients with advanced ovarian cancer, malignant peritoneal mesothelioma, breast cancer, and gastroesophageal cancer." (PMID 40574837, 2025).
malignant rhabdoid tumor (1 paper, 2022). "MUC16, OPN, AFP, and MSLN gene expression were highly expressed in all malignant rhabdoid tumor cell lines (CHLA-02, CHLA-05, and G401)." (PMID 35954348, 2022). "AFP, MSLN, MUC16, OPN, and MT1-MMP/MMP14 may serve as biomarkers for human malignant rhabdoid tumor detection and therapeutic targets." (PMID 35954348, 2022). "GM6001 significantly decreased ATRT cell proliferation and the gene expression of MSLN, OPN, and several mesenchymal markers, suggesting that inhibition of MMPs may reduce the aggressiveness of rhabdoid cancer cells." (PMID 35954348, 2022).
mesenchymal tumors (1 paper, 2024). "Mesothelin expression between epithelial and mesenchymal tumors, and benign and malignant tumors, were compared to investigate the potential relationship between mesothelin expression and the cell of origin, and its expression and malignant nature of tumors, respectively." (PMID 39315086, 2024).
mucinous tumors (1 paper, 2023). "Gastrointestinal and mucinous tumors often express markers of gastrointestinal differentiation: CK20 and CDX2, while OSMC expressed the markers of Mullerian epithelium: ER, PR, CA125, mesothelin." (PMID 36670456, 2023).
neuroectodermal tumors (1 paper, 2019). "GD2 is known to be expressed on neuroectodermal tumors and is, besides IL13RA2 and mesothelin, one of the few CAR-T cell targets to have produced solid tumor regression." (PMID 31500597, 2019).
pancreatitis (1 paper, 2020). Inflammation of the pancreas. "MSLN expression was observed in all cancer tissues by immunohistochemistry, while its absence was consistently noted in non-cancerous pancreatic ductal epithelium in patients with and without pancreatitis." (PMID 33196692, 2020).
primary sclerosing cholangitis (1 paper, 2022). "Expression of mesothelin was detected in activated Portal Fibroblasts, which are the major contributors to cholestatic liver fibrotic diseases such as primary and secondary biliary cholangitis and primary sclerosing cholangitis." (PMID 36358290, 2022).
prostate tumors (1 paper, 2025). "In line with previous studies, we found that mesothelin expression is infrequent in primary prostate tumors, but shows increased expression in metastatic samples." (PMID 40427042, 2025). "Previous research has reported the rare expression of mesothelin in primary prostate tumors." (PMID 40427042, 2025).
renal dysfunction (1 paper, 2021). "The concentrations of calretinin and mesothelin increased with increased cystatin C reflecting renal dysfunction." (PMID 34768395, 2021).
retinal vein occlusion (1 paper, 2025). An occlusion of the retinal vein. "Upregulated levels of MSLN are reported in patients with retinal vein occlusion." (PMID 40471493, 2025).
salivary gland carcinoma (1 paper, 2018). A carcinoma that arises from the major or minor salivary glands. "In order to examine the anti-tumor efficacy of MSLN-specific CAR-expressing CD8 T cells against SGC, we utilized six kinds of cancer cell lines including A-253 cells, which were derived from salivary gland carcinoma and moderately expressed MSLN." (PMID 30558663, 2018). "We examined the expression of mesothelin molecules in salivary gland cancers and the efficacy of adoptive cell therapy based on mesothelin-specific chimeric antigen receptor transduced T cells." (PMID 30558663, 2018). "The expression of mesothelin molecule was studied in salivary gland cancer samples obtained from 16 patients as well as a salivary gland cancer cell line (A-253) and five other cell lines." (PMID 30558663, 2018). "The use of adoptive transfer with mesothelin-specific chimeric antigen receptor-expressing CD8 T cells against salivary gland cancers is an effective therapy and invariant natural killer T cells are expected to be used in adjuvant treatment for T cell-based immunotherapy." (PMID 30558663, 2018).
Thrombocytopenia (1 paper, 2024). A reduction in the number of circulating thrombocytes. "MPF expression in the lungs possibly exhibits beneficial effects on the prompt recovery from thrombocytopenia via accelerated megakaryocytopoiesis/thrombopoiesis in the lungs of Euarchontogliran species that retain a functional MPF portion of the MSLN gene." (PMID 39315086, 2024).
uterine tumor (1 paper, 2020). "In the present study three human uterine tumor models which express Mesothelin at different levels were used to explore the efficacy of an anti-Mesothelin antibody drug conjugate (Anetumab ravtansine)." (PMID 32815024, 2020).
Warthin tumor (1 paper, 2021). An adenoma characterized by an oncocytic, often papillary, epithelial component, dense lymphoid stroma, and cystic spaces. "The concept of MSLN expression not representing a universal parameter of malignancy is also supported by the frequent MSLN expression in various benign tumors, including Brenner tumors of the ovary, as well as Warthin tumors, pleomorphic adenomas, and basal cell adenomas of the salivary glands." (PMID 33917081, 2021).